RNU6-1235P (RNA, U6 small nuclear 1235, pseudogene)
Gene: Small nuclear RNA gene on chromosome 15 (21,307,749 to 21,307,855, forward strand). Ensembl gene ENSG00000207289.
Homologues: Orthologues: macaque U6 (92% identical), rat U6 (84% identical). Paralogues in human: RNU6-498P (100% identical), U6 (100% identical), RNU6-331P (95% identical), RNU6-25P (91% identical), RNU6-38P (91% identical), RNU6-1 (90% identical), RNU6-2 (90% identical), RNU6-20P (90% identical), RNU6-3P (90% identical), RNU6-41P (90% identical), RNU6-4P (90% identical), RNU6-5P (90% identical), and 1287 more.